STEAP1 (STEAP family member 1)
Diseases named in the same sentence as STEAP1 in open-access papers (continued):
Sharing a sentence is not in itself a finding about the gene and the disease.
tumor (continued). "After the repeated stimulations with STEAP1+ tumor cells, the majority of both JK10 and JK11 CAR T cells acquired an EM phenotype." (PMID 38203757, 2024). "We investigated this question in vitro by subjecting the CAR T cells to six repeated stimulations from STEAP1+ tumor cells over 21 days while monitoring their expansion and phenotypic development." (PMID 38203757, 2024). "The Six Transmembrane Epithelial Antigen of the Prostate 1 (STEAP1) protein has been indicated as an overexpressed oncoprotein in prostate cancer (PCa), associated with tumor progression and aggressiveness." (PMID 37047621, 2023). "The possible mechanism of STEAP1 promoting tumor proliferation and metastasis is by acting as a channel for small molecules that are involved in intercellular communication." (PMID 37270661, 2023). "All mice that received mouse STEAP1-mBBζ CAR T cells demonstrated a decrease in tumor burden within the first week of treatment initiation based on BLI." (PMID 37041154, 2023). "Due to its high tumor specificity and membrane-bound localization, STEAP1 is currently considered an oncogene and a promising therapeutic target for PCa." (PMID 37047621, 2023). "The third group is the relatively new six-transmembrane epithelial antigen of prostate-1 (STEAP-1) family of proteins, localized in the plasma membrane of epithelial cells and known to have a role in cell adhesion and tumour invasiveness." (PMID 36874351, 2023). "Overall, these analyses indicate that CBD-IL-12 treatment reverts the hostile immunosuppressive tumor milieu to a proinflammatory state and broadens antitumor activity in conjunction with adoptively transferred STEAP1-mBBζ CAR T cell therapy." (PMID 37041154, 2023). "Overall, STEAP1 seems to enhance tumor proliferation and aggressiveness, making it a potential PCa biomarker and therapeutic target." (PMID 36768273, 2023). "STEAP1 is now drawing attention as a promising therapeutic target because of its tumor specificity and membrane-bound localization." (PMID 37909017, 2023). "All patients had an immunohistochemistry of STEAP-1 antigen presence of 1+ or above on tumour tissue." (PMID 36874351, 2023). "Reassuringly, STEAP1-BBζ CAR T cell therapy at a dose sufficient to induce antitumor activity did not lead to evident systemic toxicities in hSTEAP1-KI mice including on-target off-tumor toxicities at sites of human STEAP1 expression." (PMID 37041154, 2023). "Further, the conjugation of anti-STEAP1 antibodies with monomethyl auristatin E, a potent antimitotic agent, has shown potential in reducing tumor volume and delaying castration-resistant PCa." (PMID 36768273, 2023). "The two SwR-STEAP1 CAR T cell variants were harvested after 21 days and co-cultured with STEAP1+/− tumor cells (wild-type 22Rv1 and 22Rv1-KO), as well as with 22Rv1 cells overexpressing TGFβ (22Rv1-TGFβ) or supplemented with rhTGFβ (22Rv1+rhTGFβ)." (PMID 36830995, 2023). "Close investigation of the tumor immune microenvironment revealed that adding CBD-IL-12 to STEAP1-BBζ CAR T cell therapy induces tumor stromal reversion and enhances activated macrophages and cDC1 while reducing tumor-associated neutrophils." (PMID 37041154, 2023). "The two SwR-CAR constructs (JK59 and JK69) were expressed at similar levels and conferred both CD4+ and CD8+ T cells with STEAP1-specific anti-tumor activity." (PMID 36830995, 2023). "Serial BLI revealed rapid disease progression in mice treated with untransduced T cells and CBD-IL-12 while those receiving STEAP1-BBζ CAR T cells in combination with CBD-IL-12 therapy demonstrated a significant delay in tumor progression." (PMID 37041154, 2023).
tumor (continued). "The in vivo efficacy of mouse STEAP1-mBBζ CAR T cells was validated in a disseminated RM9-STEAP1-fLuc tumor model in NSG mice." (PMID 37041154, 2023). "The animal data indicated that STEAP1 CAR T cells retained their anti-tumor activity in vivo, and exerted tumor control." (PMID 35860008, 2022). "To investigate how the CAR T cells proliferated and responded to long-term stimulation from STEAP1+ tumor cells, we thawed CAR T cells and performed a 21-day co-culture assay of the T cells with irradiated 22Rv1 cells." (PMID 35860008, 2022). "To confirm that the sequences were correct, we generated a synthetic mAb, called Oslo-1, incorporating the identified binding sequences, and tested if this mAb would bind to STEAP1 by staining a panel of tumor cell lines for flow cytometry." (PMID 35860008, 2022). "We found that STEAP1 was upregulated in tumor tissues, while the expression level of STEAP2 was significantly downregulated." (PMID 35346237, 2022). "Here, the CAR T cells infiltrated tumors and significantly inhibited tumor growth and extended survival in a STEAP1-dependent manner." (PMID 35860008, 2022). "The promoter methylation levels of STEAP1 between normal and tumor tissues exerted significant differences in 15 cancers such as BLCA, BRCA, and CESC." (PMID 35313641, 2022). "STEAP1 CAR T cells, as well as T cells with the irrelevant CD19 CAR and NT T cells, were co-cultured with STEAP1+ tumor cells at different effector-to-target (E:T) ratios." (PMID 35860008, 2022). "The STEAP1 belongs to the group of metalloreductases and is involved in tumor cell proliferation and suppresses apoptosis." (PMID 35216235, 2022). "STEAP1 was previously validated as a promising target to discriminate adjacent and tumor samples and a useful tool for antibody therapies in different solid tumors." (PMID 35313641, 2022). "In cancer forms where peritoneal metastases represent a key development, several studies have indicated that STEAP1 promotes tumor invasion into the peritoneum." (PMID 35860008, 2022). "This includes STEAP1-specific target killing and production of multiple cytokines in vitro, and potent anti-tumor activity in vivo, accompanied by CAR T cell expansion and infiltration into STEAP1+ tumors." (PMID 35860008, 2022). "STEAP1 was an underlying target for prognostic prediction in different cancer types and a potential biomarker of TMB, MSI, tumor microenvironment, and chemosensitivity." (PMID 35313641, 2022). "With TCR-based immunotherapy targeting tumor-associated antigens and metastatic drivers of EwS, such as CHM1, STEAP1, PAPPA, and PRAME, our group previously achieved efficacious in vitro and in vivo cytotoxic targeting of HLA-A*02:01+ EwS." (PMID 36428578, 2022). "The tumors grew readily in the mice that were treated with CD19 CAR T cells or NT T cells, whereas the mice treated with STEAP1 CAR T cells displayed a substantial inhibition of tumor growth." (PMID 35860008, 2022). "The TRAMP-C1 xenograft tumor model with the KO cells and control cells showed that when STEAP-1 is knocked out, the immune protection against the tumor was suppressed." (PMID 34358202, 2021). "The over-expression of STEAP1 enhances cancer cell proliferation and contributes to tumor development and aggressiveness." (PMID 34576175, 2021). "LDH and xenograft tumor assays showed that STEAP1 KO suppresses the CTL response against TRAMP-C1 cells." (PMID 34358202, 2021). "Although reports on down-regulation of STEAP1 expression in tumor tissues are limited, they evoke further studies to investigate a potential anti-cancer role of STEAP1 in cancers." (PMID 34778263, 2021). "T cell-mediated cytotoxicity, measured by contact-dependent detachment of adherent tumor cells, of STEAP1-specific CD4+ T cells (tgCD4) was initially observed after 46 days of culture." (PMID 32610710, 2020).
tumor (continued). "Data has shown that gene STEAP1 is closely related to communication between the adjacent cells, and it seemed to be beneficial for the occurrence and development of tumours." (PMID 33128353, 2020). "STEAP1 expression was analyzed via qRT-PCR and western blotting in 40 tumor and tumor-adjacent normal tissue specimens from LUAD patients." (PMID 32265985, 2020). "Based on previous observations, we postulated strong antitumor potential of tumor-redirected CD4+ T cells transduced with an HLA class I-restricted TCR against a STEAP1-derived peptide." (PMID 32610710, 2020). "The in vivo animal experiments showed that STEAP1 knock down, resulted in a decrease in the subcutaneous tumour and peritoneal tumour formation." (PMID 33128353, 2020). "We show that formulating the DNA vaccine STEAP1 with Flt3L-Fc mobilized DCs to the site of injection and resulted in a significant increase in the antigen-specific immune response to the target tumor antigen." (PMID 32161596, 2020). "STEAP1 over-expression in prostate cancer and its bone metastases has been very well documented, showing correlation between increased expression and tumor aggressiveness." (PMID 32290196, 2020). "Lastly, we sought to determine the relevance of the addition of CD80-Fc with the STEAP1 vaccine in a tumor challenge model." (PMID 32161596, 2020). "This study was conducted to examine the role of tumor-redirected MHC class I-restricted CD4+ in comparison to tumor-redirected CD8+ T cells against a STEAP1-derived HLA-A*02:01 restricted peptide." (PMID 32610710, 2020). "Through this experiment, we verified the effect of STEAP1 on tumour cell invasion and metastasis in vivo." (PMID 33128353, 2020). "Compared with mock transduced MKN45 cells, STEAP1 silencing completely inhibited (shRNA-1) or significantly attenuated (shRNA-1) the growth of tumor." (PMID 30246786, 2018). "Specificity of 89Zr-trastuzumab tumor uptake was demonstrated by the presence of only weak 89Zr-anti-STEAP1 signal in separate Fo2-1282 brain grafts (right)." (PMID 28493046, 2017). "We have previously shown for the STEAP1 tumour antigen that a one log reduced dose of the vaccines given at one week intervals was able to stimulate IFN-γ responses comparable with the ones generated by the standard dose immunisations." (PMID 28537896, 2017). "Upon establishment of palpable tumours, mice were primed with ChAdOx1 vectors expressing STEAP1 or control antigen GFP, and 3 weeks later boosted with the respective MVA vectors." (PMID 27052571, 2016). "After adjustment for potential confounders, we determined that patients with low STEAP1 expression in the tumor portion had significantly poor prognosis." (PMID 27104516, 2016). "Results were compared with parallel immunoPET studies performed to quantify tumor uptake of the corresponding mAbs targeting TENB2 and STEAP1 in the same tumor models." (PMID 27029064, 2016). "Modest tumour-protective efficacy of the vaccine despite strong STEAP1-specific CD8+ T-cell responses has led us to investigate potential underlying mechanisms of this phenomenon." (PMID 27052571, 2016). "Our results show that blockade of PD-1 enhances the efficacy of STEAP1 vaccination in the subcutaneous tumour model significantly improving survival of STEAP1-vaccinated mice compared to STEAP1 vaccine or anti-PD-1 therapy alone." (PMID 27052571, 2016). "We also investigated the influence of tumor grade and histology on the prognostic role of STEAP1 by further adjusting for tumor grade, histology, age, gender, and stage." (PMID 27104516, 2016). "In the LuCaP70 model 111In-anti-STEAP1 uptake was the lowest (8.2 %ID/g) accompanied by tumor growth inhibition." (PMID 27029064, 2016). "Single numerical values for individual curves were obtained for an area under the curve (AUC) analysis, which demonstrated a trend towards efficacy of STEAP1-targeting vaccine in delaying tumour progression." (PMID 27052571, 2016).
tumor (continued). "We have demonstrated for the first time the ability of the ChAdOx1–MVA vaccination strategy to induce strong sustained CD8+ T-cell responses to the tumour-specific self-antigen STEAP1 in murine models." (PMID 27052571, 2016). "This work studied monomethyl auristatin E (MMAE) ADCs against two targets in metastatic castration-resistant prostate cancer, TENB2 and STEAP1, in four patient-derived tumor models (LuCaP35V, LuCaP70, LuCaP77, LuCaP96.1)." (PMID 27029064, 2016). "In conclusion, quantitative data from immunoPET measuring relative mAb uptake patterns of TENB2- and STEAP1-targeting mAbs predict to a degree tumor growth inhibition by an ADC." (PMID 27029064, 2016). "STEAP1 is not only overexpressed in different stages and metastases of PCa, but also in a variety of other tumor types including bladder, colon and ovarian cancer." (PMID 24213236, 2012). "Integrative analyses identify DNA methylation-driven gene links based on location (H3K27ac, H3K27me3, promoters, gene bodies) pointing to mechanisms underlying dysregulation of genes involved in tumor lineage (ASCL1, AR) and therapeutic targets (PSMA, DLL3, STEAP1, B7-H3)." (PMID 40593552, 2025). "Further enhancing therapeutic efficacy, the next-generation BiTE candidate BC261 has demonstrated superior tumor eradication in preclinical models, achieving approximately 30-fold greater T cell infiltration even against tumors with low STEAP1 expression levels." (PMID 40427518, 2025). "It has been shown that inhibiting the expression of STEAP1 in tumor cells may reduce proliferation and invasion in vitro, as well as inducing cell apoptosis and inhibiting metastasis in vivo." (PMID 40299363, 2025). "Furthermore, the addition of tumor-localized IL-12 in the form of a collagen binding domain-IL-12 fusion protein enhanced the anti-tumor effect of the STEAP1 CAR T cells." (PMID 38789450, 2024). "To investigate how the STEAP1 CAR T variants responded to repeated antigen stimulation, we performed long-term assays with repeated stimulations of the JK10 and JK11 CAR T cells with STEAP1+ tumor cells." (PMID 38203757, 2024). "TIGIT was expressed in a few CAR T cells before the first stimulation with STEAP1+ tumor cells." (PMID 38203757, 2024). "Furthermore, several studies have indicated that STEAP1 promotes tumor invasion into various organs and the peritoneum." (PMID 38203757, 2024). "Serial BLI revealed rapid disease progression in mice treated with untransduced T cells while those receiving STEAP1-BBζ CAR T cells demonstrated a significant delay in tumor progression and extension of survival (97 days versus 31 days, p = 0.0018 by log-rank test)." (PMID 37041154, 2023). "In addition, STEAP1 overexpression has been suggested to be a driving force for tumor initiation and progression." (PMID 36768273, 2023). "We subsequently expanded clonal RM9-STEAP1-fLuc lines to determine whether the observed tumor antigen escape could be a result of pre-existing heterogeneity in STEAP1 expression." (PMID 37041154, 2023). "However, in order to overcome the main limitations of this study, further studies must be addressed to explore the role of STEAP1 in PCa cells treated with chemotherapeutic drugs, namely the use of genetically engineered animal models and tumor xenografts." (PMID 37047621, 2023). "Furthermore, the experiments with the STEAP1 knockout 22RV1 line confirmed that the in vivo efficacy was dependent on STEAP1 tumor expression." (PMID 35860008, 2022). "There was a reduction in tumor burden in the STEAP1 CAR T group, compared with controls." (PMID 35860008, 2022). "Furthermore, high promoter methylation of STEAP1 correlated to high STEAP1 expression levels in tumor samples of CESC, COAD, ESCA, HNSC, KIRC, LUSC, and PAAD and low methylation levels was associated with lower STEAP1 expression in TGCT and UCEC." (PMID 35313641, 2022).
tumor (continued). "Furthermore, the T cells expressing the STEAP1 CAR appeared to preferentially home to or expand in the tumor, as nearly all T cells in the tumor expressed RQR8, while the majority in the peripheral blood did not." (PMID 35860008, 2022). "Therefore, future studies on the function of STEAP1 in cell death, proliferation, and tumor migration with wet-lab approaches need to be explored." (PMID 35313641, 2022). "The expressions of STEAP1 between normal and tumor tissues were analyzed using TCGA and GTEx." (PMID 35313641, 2022). "In addition, several studies exploring the role of STEAP1 in cancer cells showed that its overexpression inhibits apoptosis and induces epithelial to mesenchymal transition, ultimately contributing to tumor progression and aggressiveness." (PMID 35313641, 2022). "This may reflect that the STEAP1 CAR T cells migrated to tumor, and that NT cells have a growth advantage, as often observed with cells not subjected to transduction and ectopic gene expression." (PMID 35860008, 2022). "There may be off-tumor effects on other tissues that express STEAP1, namely, MSC-derived stromal tissues." (PMID 36011027, 2022). "STEAP1 is an ion channel or transporter that plays a role in cell adhesion and may promote tumor proliferation and invasion by regulating ion concentrations such as Na +, K +, Ca 2+, and small molecules." (PMID 35346237, 2022). "Recent studies have shown that STEAP1 acts as an oncogene, showing that its overexpression in several human cancers contributes to tumor progression and aggressiveness through the inhibition of apoptosis and stimulation of cell proliferation, invasion and epithelial–mesenchymal transition." (PMID 34833128, 2021). "The oxidative stress that results from STEAP1 overexpression may enhance tumor aggressiveness through the activation of genes involved in cell proliferation and invasion." (PMID 34833128, 2021). "The unique expression pattern of STEAP1 makes it an excellent target for tumor vaccines." (PMID 34358202, 2021). "The overexpression of STEAP1 was conserved between male and female patients; however, was not significantly different between male and female patients (P<0.05 compared to tumor adjacent normal controls)." (PMID 31949502, 2020). "Moreover, we analyzed STEAP1 expression in 57 pairs of matched specimens of tumor tissue and tumor-adjacent normal tissue from TCGA database from one patient (P < 0.05)." (PMID 32265985, 2020). "A phase I study of the DSTP3086S (the humanized IgG1 anti-STEAP1 monoclonal antibody linked to the potent anti-mitotic agent - monomethyl auristatin E (MMAE) in patients with mCRPC showed its good tolerability and anti-tumor activity." (PMID 32290196, 2020). "Of note, we could not detect any effect of anti-PD-1 mAb treatment on the magnitude of STEAP1-specific T-cell responses in circulation, suggesting that the observed synergistic effect could be taking place at the tumour site." (PMID 27052571, 2016). "Firstly, the TRAMP-C1 cell line has been previously reported to express low levels of MHCI molecules that could hamper presentation of STEAP1 epitopes on tumour cells." (PMID 27052571, 2016). "Dose-dependent tumor uptake was measured for 111In-anti-STEAP1." (PMID 27029064, 2016). "STEAP1 therefore appears to have as yet unconfirmed roles in tumor malignancy and may therefore represent a potential target for therapeutic strategies." (PMID 27104516, 2016). "To conclude, data presented in this study demonstrate that ChAdOx1–MVA-based vaccination strategy targeting prostate-associated antigen STEAP1 is able to elicit strong sustained STEAP1-specific immunity in mice and confers partial tumour protection in transplantable and spontaneous PCa mouse models." (PMID 27052571, 2016).